CASP1 (caspase 1)
Diseases named in the same sentence as CASP1 in open-access papers (continued):
Sharing a sentence is not in itself a finding about the gene and the disease.
pneumococcal infection (6 papers, 2013 to 2021). Infections with bacteria of the species streptococcus pneumoniae. "Caspase-1 was activated and the level of cleaved caspase-1 was increased within 4 h of pneumococcal infection." (PMID 26683708, 2015). "The canonical cleavage and process of pro-IL-1β to mature IL-1β is catalyzed by caspase-1; thus, we tested whether NanA promotes caspase-1 activation upon pneumococcal infection." (PMID 33777832, 2021). "In terms of inflammasome-mediated cell death, Kim and colleagues demonstrated that Streptococcus pneumoniae infection induced pyroptosis in cultured microglia as evidenced by cleavage of caspase-1 and an increase in lactate dehydrogenase release into the culture media." (PMID 30736791, 2019). "Furthermore, ROS was generated by pneumococcal infection and inhibited caspase-1 activation within 4 h of infection." (PMID 26683708, 2015). "In addition, it has been shown that ASC inflammasomes, including AIM2 and NLRP3 activate caspase-1 in pneumococcal infection and especially, pneumolysin, a major virulence factor of S. pneumoniae, activate NLRP3/ASC inflammasome in a murine model of S. pneumoniae corneal infection." (PMID 26683708, 2015). "IFN-I dependent NLRP6 inflammasome activation also induces the activation of caspase 11 along with caspase 1 activation via ASC for boisterous IL18 processing and enhanced pyroptosis mediated by caspase 1 and GSDMD in Listeria and Streptococcus Pneumoniae infections." (PMID 34768828, 2021). "We also confirmed that alveolar macrophage PCD is unaltered in caspase 1−/− murine alveolar macrophages following pneumococcal infection, confirming the PCD is not caspase 1 dependent." (PMID 25293758, 2014).
pulmonary hypertension (6 papers, 2020 to 2025). Increased pressure within the pulmonary circulation due to lung or heart disorder. "In another model of hypoxia-induced pulmonary hypertension, caspase-1-/- mice showed reduced pulmonary artery muscularization and right ventricular remodeling when compared with wildtype mice." (PMID 41231039, 2025). "In line with this, another study has shown that this caspase-1 inhibitor VX-765 suppressed the progression of hypoxia- and monocrotaline-induced pulmonary hypertension." (PMID 41231039, 2025). "A study showed that caspase-1 deficiency reduces pulmonary hypertension in mice under normobaric hypoxia, mainly by reducing PASMC proliferation." (PMID 34434114, 2021). "Therefore, caspase-1 could be another therapeutic target for hypoxia-induced pulmonary hypertension." (PMID 34434114, 2021). "Similar results exhibited that EA prevented monocrotaline-induced rat pulmonary artery hypertension via inhibiting the activation of the NLRP3 inflammasome and caspase-1 in the lungs and release of proinflammatory cytokines, such as IL-β, in serum." (PMID 33294118, 2020). "Interestingly, mice lacking NLRP3 display attenuated pulmonary hypertension and a blunted inflammasome activation with decreased caspase-1, IL-18, and IL-1β levels in response to hypoxia induced pulmonary vasoconstriction." (PMID 31915037, 2020).
renal carcinoma (6 papers, 2009 to 2026). A carcinoma arising from the epithelium of the renal parenchyma or the renal pelvis. "In our study, three CASP1/5/4/12 SNPs (rs568910, rs492859, rs507879) were associated with an increased risk of renal cancer, while one SNP (rs1785883) was associated with a decreased risk." (PMID 19603096, 2009). "Three regions containing genes associated with renal cancer were identified: caspase 1/5/4/12(CASP 1/5/4/12), epidermal growth factor receptor (EGFR), and insulin-like growth factor binding protein-3 (IGFBP3)." (PMID 19603096, 2009). "We observed that individuals with CASP1/5/4/12 haplotype (spanning area upstream of CASP1 through exon 2 of CASP5) GGGCTCAGT were at higher risk of renal cancer compared to individuals with the most common haplotype (OR:1.40, 95% CI:1.10–1.78, p-value = 0.007)." (PMID 19603096, 2009). "In addition, with a haplotype-based sliding window method, we identified the same genes with regions that were associated with renal cancer risk at a FDR level <10%: CASP1/5/4/12, EGFR, IGFBP3, and VCAM1." (PMID 19603096, 2009). "Exogenous expression of CASP1 markedly reduced the growth of renal cancer cells in vitro and in vivo, and silencing CASP1 activity resulted in the establishment of solid tumors." (PMID 28388569, 2017). "Wedetected slight bands for cleaved caspase 1 isoforms in samples of SF-295glioblastoma cells and UO-31 renal cancer cells." (PMID 23144724, 2012). "We identified both haplotypes and SNPs in CASP1/5/4/12, EGFR, and IGFBP3 that were statistically significantly associated with risk of renal cancer." (PMID 19603096, 2009). "In summary, the results from this study suggest that genetic polymorphisms and haplotypes within the CASP1, CASP5, EGFR, and IGFBP3 genes are associated with renal cancer risk." (PMID 19603096, 2009). "In conclusion, our evaluation has identified common genetic variants in CASP1, CASP5, EGFR, and IGFBP3 that could be associated with renal cancer risk." (PMID 19603096, 2009).
Shock (6 papers, 2011 to 2025). The state in which profound and widespread reduction of effective tissue perfusion leads first to reversible, and then if prolonged, to irreversible cellular injury. "In a rat model of blunt chest thorax trauma and hemorrhagic shock with subsequent resuscitation, monocytes express lower levels of caspase-1 in response to ethanol administration 2 hours before injury." (PMID 34084163, 2021). "Our finding regarding caspase-1 protein are in accordance with a recent report showing that mRNA expression of the inflammasome components ASC and caspase-1 is reduced in monocytes of patients with septic shock." (PMID 21244670, 2011).
Venous thrombosis (6 papers, 2016 to 2025). Formation of a blood clot (thrombus) inside a vein, causing the obstruction of blood flow. "And the deficiency of caspase-1 or GSDMD is identified to block flow restriction–induced venous thrombosis, but also renders monocytes and macrophages insensitivity to pyroptotic cell death." (PMID 37063905, 2023). "And caspase-1 inhibitors can effectively repress pyroptosis, showing useful approaches for alleviating ECs damage-induced thrombosis in APS." (PMID 37063905, 2023). "Studies show that PAD4 supports NLRP3 inflammasome assembly, activating the canonical NLRP3 inflammasome pathway, leading to caspase-1 activation, inducing neutrophil NETosis, a regulated form of neutrophil cell death characterized by the release of NETs, and promoting venous thrombosis in mice." (PMID 40520933, 2025). "The knockdown of miR-513c-5p aggravated venous thrombosis and propagation by enhancing caspase-1-mediated pyroptosis, while the overexpression of miR-513c-5p could alleviate DVT formation via inhibiting caspase-1 expression." (PMID 35445025, 2022). "NLRP3 and cleaved caspase-1 expression were significantly elevated in the atrium of MS patients with thrombus strongly indicating that for the first time, and to the best of our knowledge, that NLRP3 inflammasomes were activated and IL-1β was associated with thrombosis in MS patients." (PMID 26930272, 2016).
Yersinia infection (6 papers, 2020 to 2024). "In Rip1-/- mice, FLDMs exhibited spontaneous MLKL activation and Yersinia infection led to reduced activation of caspase-1, GSDMD, caspase-3, caspase-7 and caspase-8 compared to wild-type-infected FLDMs." (PMID 39513865, 2024). "RIPK3/MLKL-induced programmed necrosis also activates NLRP3, presumably via potassium efflux, thereby providing another route to caspase-1 engagement during Yersinia infection, even when caspase-8 cannot be activated." (PMID 39058785, 2024). "It has been suggested that co-assembly of ASC, NLRP3, RIPK3, caspase-1, and caspase-8 triggers PANoptosis during Yersinia infection." (PMID 39058785, 2024). "The NOD-like receptor signal transduction pathway and the Yersinia infection pathway can activate caspase-1 by the inflammasome of the multimeric protein complex." (PMID 34920753, 2021). "Whether caspase-8 and caspase-1 are activated downstream of caspase-4 or are acting in a parallel pathway during Yersinia infection of human IECs is unknown." (PMID 37615436, 2023). "In certain settings such as during Yersinia infection of macrophages, CASP8 is able to substitute for pro-pyroptotic CASP1 and CASP11 to cleave GSDMD and execute death." (PMID 33126536, 2020). "In cells lacking NLRP3, ASC or NLRC4, caspase-1 is activated and IL-1β and IL-18 are still secreted upon Yersinia infection, suggesting that other inflammasomes are involved." (PMID 39513865, 2024). "The phenomenon that caspase-1 activation requires caspase-8 but is independent of inflammasome components or the adaptor ASC was also reported in Yersinia infection of bone marrow–derived macrophages (BMDMs)." (PMID 34437534, 2021). "Although the NLRP3 inflammasome is activated in response to Yersinia infection or IKK/TAK1 blockade, NLRP3 and the adaptor ASC do not contribute to either caspase-8 or caspase-1 activation or cytotoxicity." (PMID 39058785, 2024). "Despite the lack of a requirement for ASC in caspase-8 or caspase-1 activation or cell death, ASC forms large oligomers in response to YopJ activity, suggesting that ASC complexes play an as-yet-undefined role in Yersinia infection." (PMID 39058785, 2024).
acne (5 papers, 2021 to 2023). An inflammatory process of the sebaceous glands which is characterized by comedones, nodules, papules and/or pustules on the skin. "The activation of the NLRP3 inflammasome promotes the maturation of caspase-1 and triggers the release of the downstream acne-pathogenic cytokines IL-1β and IL-18, which subsequently activates the secondary inflammatory mediators, including IL-6 and IL-832." (PMID 38062074, 2023). "Since NLRP3 is the first mediator in the activation of the inflammasome pathway, inhibition of NLRP3 expression may inhibit the next step of the pathway, in which caspase-1 finally activates IL-1β, resulting in the development of acne." (PMID 36624865, 2022). "It is worth noting that both NLRP3 active caspase-1 are expressed by tissue macrophages CD86+ in acne lesions, which also suggests the participation of inflammasome complexes in acne pathogenesis." (PMID 35329904, 2022). "In the previous study, researchers have identified that caspase-1, ASC, and NLRP3 knockdown or knockout inhibits P. acnes-induced IL-1β production in acne." (PMID 34603464, 2021). "Notably, mature caspase-1 and NLRP3 are identifiable around the pilosebaceous follicles and macrophages within acne lesions, thus affirming the potential for C. acnes-mediated NLRP3 activation in acne development." (PMID 37344849, 2023). "In light of the potential role of IL-1β in acne pathogenesis, monoclonal anti-IL-1β and/or molecules that could regulate NLRP3, caspase-1, or K+ efflux should be considered in treatments of acne." (PMID 35329904, 2022).
acute lymphoblastic leukemia (5 papers, 2010 to 2025). Leukemia with an acute onset, characterized by the presence of lymphoblasts in the bone marrow and the peripheral blood. "Another study found that a high expression of caspase 1 and NLRP3 was associated with glucocorticoid resistance in acute lymphoid leukemia (ALL) thereby resulting in a poor prognosis." (PMID 34769275, 2021). "Prior work has demonstrated that caspase-1 is involved in galectin-9-mediated apoptosis of the MOLT-4 lymphoblastic leukemia cell line; we found that caspase 8 mediated antigen induced cell death of HCV-specific CTLs." (PMID 20209097, 2010). "Upregulation and serving as a prognostic biomarker in acute lymphoblastic leukemia (ALL), and regulating gefitinib resistance in lung adenocarcinoma cells through interactions with miR-377/CASP1 axis are other recent discovered activities of SGHG5." (PMID 40486167, 2025).
allergic rhinitis (5 papers, 2015 to 2025). Inflammation of the nasal mucous membranes caused by an IgE-mediated response to external allergens. "This compound inhibited allergic responses via the regulation of the production of IL-32 and thymic stromal lymphopoietin and nasal mucosa caspase-1 activity in a murine allergic rhinitis model." (PMID 26694364, 2015). "These outcomes support the findings in rats with allergic rhinitis, further proving that APS inhibits the activation of NLRP3 inflammatory vesicles in rats, hence lowering the production of inflammatory markers (Caspase-1, IL-1β, and ASC)." (PMID 40427385, 2025). "Data from their experiments showed decreased pro-caspase-1, pro-IL-1β, and ASC mRNA levels in both asthmatic patients and patients with allergic rhinitis." (PMID 26091108, 2015).
aneurysm (5 papers, 2018 to 2024). Bulging or ballooning in an area of an artery secondary to arterial wall weakening. "Further, aneurysm tissue also demonstrated higher mRNA expression levels of the NLRP3 pathway components caspase-1, IL-1β, and GSDMD." (PMID 41541085, 2023). "Our finding that naringenin or TFEB inhibited NLRP3 inflammasome activation and reduced IL-1β secretion during AAA is consistent with previous reports that depletion of the NLRP3, caspase-1, and IL-1β inflammasomes protect against aneurysm formation in mice." (PMID 35228523, 2022). "In human aneurysm specimens, we also found that both pyroptosis markers (NLRP3, GSDMD and CASP1) and circHipk3 were mainly concentrated in the adventitia of aneurysm tissue, which was the main site of macrophage infiltration." (PMID 39601144, 2024). "To determine if pyroptosis plays a role in human and mouse aneurysms, we evaluated markers of pyroptosis including NLRP3, CASP1, GSDMD and IL‐1β, and also analysed MMP2/9 in human aortic aneurysms and mouse AAA." (PMID 39601144, 2024). "The mRNA expression of the downstream NLRP3 pathway components caspase-1, IL-1β, and GSDMD is also increased in the aneurysm tissue compared to healthy vessels." (PMID 41541085, 2023).
apical periodontitis (5 papers, 2021 to 2025). "Caspase-1/-11 were involved in bone loss in experimental apical periodontitis." (PMID 36359010, 2022). "In addition, estrogen deficiency can induce activation of the NLRP3/caspase-1/IL-1β axis and aggravate periapical bone loss in postmenopausal patients and ovariectomized rats with periapical periodontitis." (PMID 34177950, 2021). "Pyroptosis was also significantly increased in rats with acute periapical periodontitis, resulting in increased bone loss, and this effect could be alleviated by caspase-1 inhibition, suggesting that pyroptosis levels may be related to the degree of inflammation in periapical periodontitis." (PMID 34177950, 2021). "The increased IL-1β and caspase-1 expression by Ef.LTA/butyrate was confirmed in the rat apical periodontitis model." (PMID 36977666, 2023). "Butyrate combined with lipoteichoic acid significantly increased caspase-1 activation and IL-1β secretion both in vitro and in vivo in a rat model of apical periodontitis." (PMID 37893122, 2023). "Caspase-1/-4/-5 were expressed in human apical periodontitis tissues." (PMID 36359010, 2022). "The increased expression of caspase-1 and caspase-11 in RAW264.7 cells treated with LPS was found to be significantly reduced by nanosilver, and this decreased inflammasome activity may contribute to the alleviation of canine periapical periodontitis progression." (PMID 34177950, 2021).
Brain atrophy (5 papers, 2022 to 2026). Partial or complete wasting (loss) of brain tissue that was once present. "In caspase-1-deficient mice, severe brain atrophy was significantly reduced following ZIKV-infection compared with ZIKV-infected wild-type mice." (PMID 35371036, 2022). "Furthermore, treatment of ZIKV-infected mice with a selective caspase-1 inhibitor (VX-765) reduced ZIKV-induced severe brain atrophy and reversed neuroinflammation." (PMID 35371036, 2022). "We found that retinal NLRP3 and Casp1 were very strongly correlated with retinal atrophy, an index of retinal thickness from inner limiting membrane to outer limiting membrane (r = 0.82–0.86, p<0.001–0.0001), whereas these markers had moderate correlation with brain atrophy (r = 0.41–0.47, p<0.05)." (PMID 40667156, 2025).
Candida infection (5 papers, 2010 to 2024). "Mice deficient in NLRP3, ASC, or caspase-1 have increased fungal proliferation and decreased survival during systemic candidiasis." (PMID 34964702, 2022). "We next explored the mechanism responsible for the discrepant outcomes of candidiasis in Casp1/11- and Gsdmd-deficient mice." (PMID 34795266, 2021). "CASP1 also enhances adaptive immunity to candidiasis by promoting the differentiation and function of Th17 cells." (PMID 38003833, 2023). "CASP1 plays a key role in innate immunity to candidiasis by inducing pyroptosis, which is a form of inflammatory cell death that releases cytokines and alarmins." (PMID 38003833, 2023). "During systemic candidiasis, candidalysin contributes to NLRP3 inflammasome activation with subsequent caspase-1-dependent IL-1β secretion and renal neutrophil recruitment." (PMID 34964702, 2022). "IL-1β production is required for an effective host response to Candida infection, and mice lacking critical inflammasome components such as NLRP3, ASC, or caspase-1 are hypersusceptible to C. albicans-induced sepsis." (PMID 34795266, 2021).
chronic obstructive pulmonary disease (5 papers, 2017 to 2025). A chronic and progressive lung disorder characterized by the loss of elasticity of the bronchial tree and the air sacs, destruction of the air sacs wall, thickening of the bronchial wall, and mucous accumulation in the bronchial tree. "TREM1 promoted inflammation in patients with chronic obstructive pulmonary disease by activating caspase-1-induced pyroptosis." (PMID 38333413, 2024). "The bacterium ultimately induces apoptosis through caspase-1 activation, triggering recurrent replication cycles and culminating in Legionella pneumonia.This 70-year-old patient had a history of smoking and chronic obstructive pulmonary disease." (PMID 41035666, 2025). "In a mouse model of chronic obstructive pulmonary disease (COPD), dexamethasone not only downregulated NLRP3, caspase-1, and IL-1β but also upregulated the levels of SOD." (PMID 34512868, 2021).
Cirrhosis (5 papers, 2020 to 2025). A chronic disorder of the liver in which liver tissue becomes scarred and is partially replaced by regenerative nodules and fibrotic tissue resulting in loss of liver function. "Previous studies have found higher NLRP3 and caspase-1 expression levels in liver of patients with cirrhosis." (PMID 37370025, 2023). "The NLRP3 inflammasome is significantly activated in a CCL4-induced mouse model of cirrhosis, which aggravates hepatocyte death and cirrhosis through the NLRP3/caspase-1/GSDMD classical pyroptosis pathway." (PMID 37370025, 2023). "Among these genes, altered methylation of Fibroblast growth factor receptor 2 (FGFR2) and Caspase 1 (CASP1), which are involved in epithelial to mesenchymal transition, inflammation and fibrotic processes, seemed to play a crucial role in the progression to cirrhosis and HCC." (PMID 32340286, 2020).
dementia (5 papers, 2013 to 2026). Loss of intellectual abilities interfering with an individual's social and occupational functions. "NLRP3, an inflammasome receptor, generates a chronic inflammatory environment and regulate the maturation of its downstream target Caspase-1, followed by apoptosis and cytokine release, leading to the development and progression of dementia." (PMID 38284892, 2024). "Interestingly, CASP1 and SPN are regulated in dementia and the supplemented diets in the opposite direction, indicating that the supplements may be beneficial in reducing the risk of dementia." (PMID 33302351, 2020). "Up-regulation of caspase-1 and caspase-7, but not TUNEL-positive cells, have been reported in the brains of patients with a Clinical Dementia Rating of 0.5." (PMID 23469123, 2013).